INS (insulin)
Diseases named in the same sentence as INS in open-access papers (continued):
Sharing a sentence is not in itself a finding about the gene and the disease.
diabetes (continued). "Insulin pumps offer significant advantages, including improved glucose regulation, reduced risk of hypoglycemia, and lower incidence of diabetes-related hospitalizations." (PMID 40217595, 2025). "Insulin-deficient subtypes predominated, accounting for 77.5% of all diabetes cases and 66.0% of prediabetes cases." (PMID 40678231, 2025). "The incorrectly folded PROINS, resulting from these genetic alternations, has been associated with impaired INS production and the onset of diabetes, including mutant INS-gene-induced diabetes of Youth (MIDY) and type 2 diabetes (T2D)." (PMID 40052150, 2025). "Diabetes is a chronic metabolic disease characterized by hyperglycemia caused by a decrease in the synthesis and/or action of insulin." (PMID 40496562, 2025). "A study has reported that recently diagnosed type 2 diabetes mellitus requiring insulin therapy was associated with an increased risk of major fractures within five years." (PMID 40564223, 2025). "This financial burden results in irregular insulin use and poor glycaemia control, increasing the risk of diabetes-related emergencies such as DKA." (PMID 40938912, 2025). "Type 2 Diabetes Mellitus, hyperinsulinemia, and both systemic and brain insulin resistance, all of which show dysregulation of insulin signaling, increase the susceptibility to developing AD." (PMID 40006083, 2025). "As a hallmark of type 2 diabetes mellitus, insulin resistance (IR) refers to a state of reduced sensitivity and responsiveness to the action of insulin." (PMID 40405981, 2025). "Our findings align with studies indicating hormonal changes as significant factors in diabetes risk, as they highlight the role of β-cell function and insulin sensitivity." (PMID 40361840, 2025). "Adipose tissue of the diabetes-susceptible mice was less insulin sensitive with ~ 200 differentially expressed mature miRNAs compared to diabetes-resistant mice." (PMID 41361331, 2025). "Diabetes mellitus (DM) is a long-term metabolic disease marked by elevated blood sugar levels brought on by deficiencies in either the action or secretion of insulin, or both." (PMID 41333488, 2025). "While glucose monitoring frequency and insulin bolus dosing are both indicators of engagement with diabetes self‐management, higher TIR has a closer association with increased rates of user engagement with isCGM than with increased rates of bolus dosing." (PMID 41039947, 2025). "Micronutrient deficiencies affect insulin signaling and glucose metabolism, which speeds up the onset and progression of complications, making this “hidden hunger” worsen the burden of diabetes." (PMID 41190158, 2025). "The American Diabetes Association’s Standard states that perioperative patients require more frequent blood glucose monitoring, particularly when insulin therapy is administered." (PMID 40198903, 2025). "Diabetes treatments, including insulin, sulfonylurea, and thiazolidinedione, are associated with an elevated risk of extremity fractures." (PMID 40542285, 2025). "The Rotterdam study already showed in 1996 that diabetes patients on insulin had an increased risk of developing dementia, specifically AD." (PMID 41146261, 2025). "A Dutch study conducted on overweight and obese adolescents revealed that lower TST was associated with increased insulin sensitivity, particularly among those with a family history of non-insulin-dependent diabetes mellitus." (PMID 40421240, 2025). "Emerging evidence associates the use of isCGM with the reduction in diabetes-related events and all-cause hospitalizations in PwD following therapies with less intensive insulin regimen or glucose-lowering oral drugs." (PMID 40565985, 2025). "The early metabolic alterations in non-insulin-treated diabetes likely underlie the observed structural remodelling." (PMID 41153651, 2025). "Diabetes is either caused by the pancreas’s inability to produce insulin or the body’s failure to utilize insulin effectively." (PMID 40507585, 2025).
diabetes (continued). "In this cross-sectional study of the association of accessibility and reimbursement with glycemic outcomes, we observed that HbA1c levels were associated with the accessibility of modern diabetes technologies and insulin." (PMID 40864470, 2025). "Healthcare providers should incorporate discussions about sexual health and hypoglycemia risk into routine diabetes care, particularly for high-risk groups such as insulin users and T1DM patients." (PMID 41030722, 2025). "Medical parameters related to the severity of diabetes were found to be associated with a significant risk for depression, specifically insulin use and the presence of cardiovascular disease, for which the correlation was most significant." (PMID 40658313, 2025). "According to research in Diabetes Care, consistent aerobic exercise improves insulin sensitivity and glycemic control, thereby lowering the risk of type 2 diabetes in older adults." (PMID 40530242, 2025). "Both biochemical parameters (Glucose, Triglyceride, HDL, Albumin, WBC) and clinical characteristics (BMI, diabetes duration >10 years, insulin use) were independently associated with glycemic deterioration." (PMID 41008733, 2025). "Excessive postprandial insulin increases have been associated with insulin resistance, metabolic dysregulation, and an increased risk of developing type 2 diabetes mellitus." (PMID 40490608, 2025). "Mutations in HNF4α are associated with MODY1, a monogenic form of diabetes characterized by β-cell dysfunction, impaired insulin secretion, and progressive hyperglycemia." (PMID 40926269, 2025). "Male cats are significantly more predisposed to diabetes compared to females due to gender differences in weight gain and insulin sensitivity." (PMID 40559766, 2025). "Diabetes mellitus is a group of metabolic disorders characterized by elevated blood glucose levels, mainly due to impaired insulin secretion, reduced sensitivity, or a combination of both." (PMID 41395370, 2025). "Although calorie-free, some can trigger insulin responses or increase cravings, possibly leading to overeating and poor glycemic control in people with or at risk for diabetes." (PMID 40873447, 2025). "Although the onset of diabetes mellitus occurs predominantly with the long-term use of glucocorticoids, short-term treatment has also been associated with impaired insulin sensitivity and hyperglycemia in healthy individuals." (PMID 40284576, 2025). "The primary cause of diabetes is the dysfunction or loss of pancreatic β-cells, leading to insufficient insulin secretion and subsequent metabolic imbalances." (PMID 40458823, 2025). "Diabetes mellitus is a disorder of carbohydrate, protein and fat metabolism caused by insufficient insulin secretion and/or insulin utilization disorder, with hyperglycemia as the main sign." (PMID 40939011, 2025). "Participants with obesity, and diabetes were exposed to a high cardiometabolic risk, illustrated by insulin resistance (high insulin and HOMA-IR index values), glucose intolerance (a rise in HbA1c levels), and dyslipidemia." (PMID 40095937, 2025). "This MR study explores the causal link between the use of exogenous insulin and the risk of OA, while also examining the intermediary roles of diabetes and smoking." (PMID 41398760, 2025). "Obesity and diabetes are closely related, and fat accumulation causes diabetes by interfering with the action of insulin." (PMID 39947694, 2025). "Diabetes is a metabolic disorder characterized by deficiency in insulin production, insulin action or both, leading to hyperglycemia in the absence of adequate treatment." (PMID 40649704, 2025). "The extracellular matrix (ECM), an important component of the skeletal muscle niche, has been shown to be affected by aging and different stages of diabetes, and it is closely linked to the phenomenon of insulin resistance in skeletal muscle." (PMID 40309438, 2025).
diabetes (continued). "Thyroid illnesses, particularly hypothyroidism (underactive thyroid) and hyperthyroidism (overactive thyroid), can have a major impact on glucose metabolism and insulin sensitivity, worsening or even causing diabetes." (PMID 41210054, 2025). "Losing weight is associated with a decrease in insulin resistance and insulin level, decreasing the risk of type 2 diabetes or improving previously diagnosed diabetes." (PMID 40146920, 2025). "In β-cells, the toxic effects of misfolded PROINS can trigger apoptosis, further exacerbating INS deficiency and promoting diabetes progression." (PMID 40052150, 2025). "The evidence shows that increased inflammation can impair the secretion of insulin, leading to insulin resistance, a well-established risk factor for type 2 diabetes mellitus." (PMID 40070482, 2025). "Type 1 diabetes mellitus (T1DM) is an autoimmune condition characterized by insulin deficiency when beta cells in the pancreas stop producing insulin." (PMID 40658159, 2025). "Statins have been shown to increase the risk of diabetes, the underlying mechanism associated with reduced insulin secretion." (PMID 40735483, 2025). "Diabetes mellitus (DM) is a complex and multifactorial disorder associated with elevated blood sugar levels, poor insulin sensitivity, and inadequate insulin production." (PMID 41216008, 2025). "Diabetes associated with WS1 requires insulin therapy, using a basal-bolus scheme or continuous subcutaneous insulin infusion (CSII)." (PMID 40988749, 2025). "Associations of serum SCFA and BCFA levels with risk of incident diabetes in overall population and by gender, with additional adjustment for insulin measurements." (PMID 40078932, 2025). "The study explores the previously unexamined link between exogenous insulin treatment for diabetes mellitus and its potential to alter the risk of osteoarthritis (OA) using Mendelian randomization (MR) to investigate a possible causal relationship." (PMID 41398760, 2025). "In summary, the genetic vulnerability to diabetes is a multifaceted phenomenon shaped by a variety of genetic mutations influencing mitochondrial functions and insulin signaling pathways." (PMID 40862129, 2025). "Diabetes mellitus (DM) is a metabolic disease characterized by chronic hyperglycemia due to multiple etiologies and is caused by defective insulin secretion and/or action." (PMID 39975983, 2025). "Growing evidence indicates that disturbed sleep architecture is associated with impaired glucose homeostasis, decreased insulin secretion and an increased risk of diabetes." (PMID 40533747, 2025). "This study demonstrates that post-coital hypoglycemia is a significant yet under-recognized complication among patients with diabetes in Al-Ahsa, affecting nearly one in five participants, with the highest risk observed in insulin users and those with T1DM." (PMID 41030722, 2025). "Lower liver density is associated with diabetes status (p = 0.007) and higher HbA1c (p = 0.03), whereas lower skeletal muscle density is associated with higher glucose (p = 0.03) and insulin (p = 0.04)." (PMID 40533477, 2025). "An imbalance in glucose metabolism, brought on by insulin resistance, inadequate insulin production, or both, is the fundamental cause of metabolic illness known as diabetes." (PMID 40005360, 2025). "This study examined changes in diabetes risk, β-cell function, and insulin sensitivity in relation to menopause." (PMID 40361840, 2025). "The pathogenesis of diabetes is multifaceted, predominantly characterized by chronic hyperglycemia that is frequently associated with insulin resistance (IR) and compromised insulin secretion." (PMID 39963239, 2025). "Diabetes technologies such as insulin pumps, continuous glucose monitors, and automated insulin delivery systems can reduce the burden associated with diabetes management and improve the quality of life in youth with T1D." (PMID 40875986, 2025).
diabetes (continued). "Recent comparative genomic analyses revealed conserved and species-specific variants in key diabetes-associated genes, such as INS, PDX1, and GLUT4, across humans, dogs, and cats." (PMID 41012437, 2025). "Changes in β-cell function and insulin sensitivity indices were tracked, and their relationship with diabetes risk was assessed." (PMID 40361840, 2025). "Maturity-onset diabetes of the young type 10 (MODY10) is a monogenic diabetes subtype caused by heterozygous mutations in the insulin gene (INS), leading to defective proinsulin processing, endoplasmic reticulum (ER) stress, and β-cell dysfunction." (PMID 40869431, 2025). "Diabetes mellitus features the loss of mass or function of β-cells responsible for producing insulin." (PMID 40707469, 2025). "Chronic inflammation in type 2 diabetes mellitus (T2DM) is closely linked to dysregulated insulin secretion including insulin resistance and disrupted immune responses." (PMID 40806100, 2025). "The absolute or relative deficiency of insulin, along with the impairment of β-cell function, is recognized as a cornerstone of diabetes pathophysiology." (PMID 41225468, 2025). "These baseline conditions suggest that women who develop diabetes later in life are more susceptible to diabetes-related risk factors, including impaired β-cell function and reduced insulin sensitivity." (PMID 40361840, 2025). "The American Diabetes Association (ADA) classifies diabetes as “a group of metabolic diseases characterized by hyperglycemia resulting from defects in insulin secretion, action or both,” within which T1DM stands out as the primary autoimmune form." (PMID 41477679, 2025). "Monogenic diabetes results from mutations in a single gene that affect insulin action or β-cell function." (PMID 41128021, 2025). "This improvement is critical for older adults, as better insulin sensitivity helps regulate blood glucose levels, reducing the risk of diabetes and its associated complications." (PMID 40530242, 2025). "Lipoatrophy, a localized loss of subcutaneous fat, is a recognized complication of insulin therapy, affecting approximately 1% of patients with type 1 diabetes mellitus (T1DM)." (PMID 40746499, 2025). "Reports from India have described an even broader mutation spectrum, including ABCC8, HNF1B, and INS variants, collectively accounting for a substantial proportion of monogenic diabetes diagnoses." (PMID 41367630, 2025). "Excessive ROS generated in mitochondria damages cellular components and interferes with insulin signaling, which contributes to insulin resistance, a hallmark of diabetes." (PMID 40290438, 2025). "The patient wasnot obese and his diabetes was characterized by onset in late adolescence,impaired insulin secretion and metabolic dysfunction-associated steatoticliver disease (MASLD)." (PMID 40840513, 2025). "Islet transplantation represents a promising therapeutic strategy for insulin-deficient diabetes, enabling the restoration of physiological insulin secretion." (PMID 41301503, 2025). "Diabetes associated with this mutation reflects primarily impaired β-cell secretion, characterized by reduced insulin and C-peptide responses, decreased urinary C-peptide excretion, and minimal insulin resistance." (PMID 41465450, 2025). "Cdk4 knockout mice display significantly reduced body size, impaired fertility, and insulin-deficient diabetes due to abnormal postnatal islet cell development." (PMID 40210435, 2025). "This leads to the apoptosis of pancreatic islet β-cells, results in insufficient insulin secretion, and eventually causes diabetes." (PMID 40535761, 2025). "Recent years have seen research that has clarified cerebral insulin resistance and defective insulin signaling as examples of pathogenic factors behind this cognitive impairment in diabetes." (PMID 39876043, 2025).
diabetes (continued). "For example, well-maintained neighborhoods are associated with physical activity, improved insulin sensitivity and lower HbA1c, while racial discrimination in healthcare is associated with higher HbA1c in adults with diabetes." (PMID 40874930, 2025). "As mitochondria play a crucial role in regulating β-cell insulin secretion, and dysfunction in this process is a hallmark of diabetes." (PMID 39835172, 2025). "Precipitating factors leading to SGLT2i‐associated ketoacidosis include reduction in insulin doses (or omission), alcohol excess and low‐carbohydrate diets." (PMID 40130476, 2025). "Among patients who already had a diagnosis of diabetes, failure to use insulin was the cause in 47 % of cases of DKA." (PMID 40037551, 2025). "As the main pathogenic mechanism tying AD and diabetes mellitus together, numerous research have concentrated on insulin, its signaling, and resistance in both peripheral and central tissues." (PMID 40381169, 2025). "The GPER has been implicated in modulating insulin sensitivity, lipid metabolism, and inflammatory pathways, all of which are crucial in diabetes pathophysiology." (PMID 40142159, 2025). "A large change in insulin sensitivity, especially during the period immediately before the onset of diabetes, increased the risk of diabetes (OR 1.88; 95% CI 1.33–2.67)." (PMID 40361840, 2025). "Genetically predicted insulin concentrations are directly associated with risk for endometrial, pancreatic, and breast cancers, and obesity, diabetes, and prediabetes each associate with basal and postprandial hyperinsulinemia." (PMID 41178720, 2025). "Diabetes is a metabolic disease characterized by a chronic increase in blood sugar levels caused by insufficient insulin secretion or insulin resistance." (PMID 39743857, 2025). "Among its subtypes, endogenous-insulin-deficient diabetes, which is characterized by markedly reduced endogenous insulin secretion and low fasting C-peptide levels, represents a clinically distinct and metabolically vulnerable subgroup." (PMID 41586239, 2025). "In our study, we included insulin product usage in reverse MR analysis and conducted multivariable MR analysis, finding that the positive causal effect of diabetes on TL became insignificant after considering insulin usage." (PMID 40299325, 2025). "The interplay of inflammation, oxidative stress, insulin resistance, and hyperglycemia perpetuates this vicious cycle, raising the risk of complications from diabetes." (PMID 41159201, 2025). "Diabetes mellitus is a chronic disease marked by prolonged hyperglycemia, which arises from defects in insulin secretion, insulin action, or a combination of both." (PMID 40124248, 2025). "Diabetes is a chronic metabolic disorder caused by insufficient insulin secretion or ineffective insulin utilization, leading to elevated blood glucose that can damage major organs." (PMID 41228635, 2025). "We hope that this study expands the understanding of the risk of diabetes and related β-cell function and insulin sensitivity changes in the period around menopause, providing insights into the susceptibility to diabetes." (PMID 40361840, 2025). "Next, we investigated the phosphorylation of associated insulin signaling pathway proteins and discovered that the majority of them were downregulated in the diabetes group." (PMID 40589410, 2025). "There is, however, limited knowledge about the contribution of TRIM to specific pathogenic processes in diabetes, such as impairment of insulin secretion, insulin resistance, or adipose inflammation, and its impact on diabetes severity." (PMID 40892509, 2025). "AhR antagonists should be explored as a potential therapeutic strategy in diabetes due to their ability to reduce inflammation, improve insulin sensitivity, and mitigate obesity-associated metabolic dysfunction." (PMID 41440753, 2025).